NPPB (natriuretic peptide B)
Diseases named in the same sentence as NPPB in open-access papers (continued):
Sharing a sentence is not in itself a finding about the gene and the disease.
Obesity (362 papers, 2007 to 2026). Accumulation of substantial excess body fat. "We, therefore, assume that low BNP levels result from a combination of factors including obesity, insulin resistance, and polymorphisms at NPPB and its promoter." (PMID 29572478, 2018). "Natriuretic peptide B is implicated in a variety of actions, including an important role in obesity and insulin resistance." (PMID 23834466, 2013). "As shown in the obesity → NPPB (Brain natriuretic peptide) or NPPA (Atrial natriuretic peptide) → MI pathway, both natriuretic peptides were belonged to the MI promotors but inhibited by obesity." (PMID 33842562, 2021). "In some patients, serum levelsof NP can be low due to several factors now established as obesity, polymorphismsin the natriuretic peptide B (NPPB) gene, African ancestry,hypercortisolism, increased androgenicity in women, insulin resistance, andcertain medications." (PMID 39076445, 2023).
COVID-19 (300 papers, 2020 to 2026). A disease caused by infection with severe acute respiratory syndrome coronavirus 2. "The Cox regression analyses suggested that 9 prognostic genes (ANPEP, OAS1, SCGB1A1, HLA‐A, NPPB, FGB, CCL2, TLR4, and SERPINE1) might act critical roles in the treatment of UCEC/COVID-19." (PMID 36969077, 2023). "Then, regression analyses indicated that 9 prognostic genes (including ANPEP, OAS1, SCGB1A1, HLA‐A, NPPB, FGB, CCL2, TLR4, and SERPINE1) might play important roles in quercetin for treating UCEC/COVID-19." (PMID 36969077, 2023).
renal failure (285 papers, 2007 to 2026). "Changes in serum levels of brain natriuretic peptide between non-acute kidney injury and acute kidney injury groups during living donor liver transplantation." (PMID 30557393, 2018).
cardiomyopathy (172 papers, 2008 to 2026). A disease of the heart muscle or myocardium proper. "Interestingly, 15 out of 20 genes found to be associated with cardiomyopathy also showed a women overexpression bias in heart tissue, as in the natriuretic peptide B-secreted cardiac hormone gene NPPB, supporting previous evidence on its involvement in sex-differential cardiovascular phenotypes." (PMID 28173793, 2017). "We also found that increased expression of cardiomyopathy markers, natriuretic peptide A (Nppa) and natriuretic peptide B (Nppb) seen in vehicle-treated NSML mice were significantly inhibited in dasatinib-treated NSML mice." (PMID 33689087, 2022). "As a well-known cardiomyopathy marker, natriuretic peptide B (NPPB) expression significantly increased in the heart tissues from DCM patients, compared with that from healthy control." (PMID 29523209, 2018). "Quantitative real-time PCR analysis showed increased expression of NPPB (A), marker of cardiomyopathy, in heart samples from DCM patients." (PMID 29523209, 2018). "We further examined the expression of molecular markers for cardiomyopathy, including natriuretic peptide A (NPPA), natriuretic peptide B (NPPB) and β-myosin heavy chain (β-MHC)." (PMID 34512174, 2021).
dyslipidemia (115 papers, 2012 to 2026). "Vice versa genetic variants of the ANP or BNP genes (NPPA, NPPB) that result in an increase in circulating levels of NPs have been associated not only with lower blood pressure, but also with protection from the metabolic syndrome in the general population." (PMID 30016962, 2018).
dilated cardiomyopathy (63 papers, 2011 to 2026). Cardiomyopathy which is characterized by dilation and contractile dysfunction of the left and right ventricles. "We also found NPPB, the gene encoding preprohormone (propro‐B‐type natriuretic peptide, preproBNP) in cardiomyocytes, as a biomarker specifically to dilated cardiomyopathy." (PMID 40657554, 2025).
atherosclerosis (60 papers, 2011 to 2025). A disease characterized by the build-up of fatty material and calcium deposition in the arterial wall resulting in partial or complete occlusion of the arterial lumen. "Renin (REN), NT-proBNP, Natriuretic peptide B (NPPB), and proprotein convertase subtilisin/kexin type 9 (PCSK9) consistently emerged as the top contributors to the atherosclerosis-related, MR-derived, and whole proteome panels." (PMID 40585252, 2025). "Moreover, the role of natriuretic peptide B in the development of atherosclerosis is not clear." (PMID 37048709, 2023).
dementia (39 papers, 2012 to 2026). Loss of intellectual abilities interfering with an individual's social and occupational functions. "Since most of the identified proteins are not present in both diseases, we performed two independent PPI analyses: the first using the proteins associated with HF (NPPB, REN, ADIPOQ, VWF, ACE, IL6, and CRP) and the second using the proteins involved in dementia (CRP, APP, MAPT, APOE, ACE, and IL6)." (PMID 40699836, 2025). "Examination of the highlighted keywords revealed the commonality between HF and dementia, namely IL6, ACE, APOE, APP, ADIPOQ, LEP, and NPPB, suggesting that these proteins may link the two pathologies." (PMID 40699836, 2025).
preeclampsia (34 papers, 2011 to 2025). Preeclampsia is a hypertensive disorder of pregnancy that is characterized by new-onset hypertension with proteinuria presenting after 20 weeks of gestation, and depending on mild or severe forms may initially present with severe headache, visual disturbances, and hyperreflexia. "Similarly, the expression of SDC1, NPPB (natriuretic peptide B), GDF15 (growth differentiation factor 15), and ADAMTS6 (ADAM metallopeptidase with thrombospondin type 1 motif 6) all had a lower expression in our experimental exposures, and all are lower in preeclampsia." (PMID 34150771, 2021).
systolic heart failure (22 papers, 2008 to 2025). Heart failure caused by abnormal myocardial contraction during systole leading to defective cardiac emptying. "NPPB is overexpressed in the heart left ventricle and heart atrial appendage and has been associated with systolic heart failure." (PMID 28974199, 2017).
ovarian carcinoma (4 papers, 2015 to 2023). A malignant neoplasm originating from the surface ovarian epithelium. "NPPB is a secreted protein that has been proven to maintain a high level in the blood of women with ovarian cancer, which indicates that NPPB may be a novel biomarker for the detection of EOC." (PMID 35646648, 2022). "Recently, Lawrenson and colleagues identified natriuretic peptide B (NPPB), a CAF-specific secretory protein, as a tumor biomarker for ovarian cancer." (PMID 26751490, 2016). "In recent years, a variety of molecular biomarkers in ovarian cancer have been identified, such as HE4, NPPB, and goosecoid homeobox." (PMID 25861644, 2015).
Cyanosis (2 papers, 2023 to 2026). Bluish discoloration of the skin and mucosa due to poor circulation or inadequate oxygenation of arterial or capillary blood. "The positive correlation of a transcript with cardiac BBLN transcript levels in TOF patient heart specimens is exemplified for the heart failure and myocardial ischemia marker, natriuretic peptide type b (NPPB), which could be induced in TOF patients with cyanosis by the low oxygen condition." (PMID 38666071, 2023).
colon adenocarcinoma (1 paper, 2019). "In this work, we identified PGC1α-induced myokines and found that only the expression of musclin, unlike that of its family member, natriuretic peptide precursor B (NppB), is almost abrogated in the muscles of colon adenocarcinoma C26-bearing mice." (PMID 31614775, 2019).
cardiovascular disease (440 papers, 2005 to 2026). "Genotypes of 10 SNPs from the NPPB and NPPA regions that encode BNP and A-type natriuretic peptide, respectively, were tested for association with NT-proBNP and prevalent cardiovascular disease and risk factors." (PMID 33720941, 2021). "Of the top 50 up-regulated hCM-specific genes we analyzed, 27 of them (54%) showed associations with at least one known cardiovascular diseases and 5 of them (NPPB, TNNT2, NPPA, RYR2, and PLN) were linked to more than 10 different types of cardiovascular diseases." (PMID 24474197, 2014). "NPPB encodes brain natriuretic peptide (BNP), which is a biomarker for cardiovascular disease." (PMID 24303131, 2013).
cancer (235 papers, 2007 to 2026). A tumor composed of atypical neoplastic, often pleomorphic cells that invade other tissues. "Kif3A that promote PCa, NPPB, a potential oncogene, and ILF‐3, a cancer stem cell upstream regulator, are downregulated by 433‐3β treatment." (PMID 40007440, 2025).
infection (99 papers, 2013 to 2026). The state of being infected such as from the introduction of a foreign agent such as serum, vaccine, antigenic substance or organism. "We validated in two cell-lines (Caco-2 and HT-29) the changes in expression of a number of genes (MT1E, NPPB, NOTCH3, CYP26A1, HEY1 and CYP1A1) found to be differentially expressed using RNAseq following infection with C. concisus UNSWCD or BAA-1457." (PMID 27677841, 2016).
NPPB also shares sentences with these, for which no sentence is quoted: heart disease (382 papers); chronic kidney disease (283); pulmonary hypertension (259); anemia (220); Sepsis (203); renal dysfunction (201); myocarditis (182); Arrhythmia (181); acute coronary syndrome (167); type 2 diabetes (159); myocardial ischemia (142); left ventricular hypertrophy (138); Myocardial fibrosis (123); chronic obstructive pulmonary disease (118); acute myocardial infarction (117); kidney disease (96); ischemia (87); pulmonary embolism (84); ischemic stroke (81); AL amyloidosis (78); Mitral regurgitation (78); Tricuspid regurgitation (70); Insulin resistance (68); angina (66); aortic stenosis (66); breast carcinoma (64); pneumonia (64); hyperlipidemia (60); pericardial effusion (60); pulmonary edema (59).
A further 642 diseases each share a sentence with NPPB in 58 papers or fewer.